CD4 (CD4 molecule)
Diseases named in the same sentence as CD4 in open-access papers (continued):
Sharing a sentence is not in itself a finding about the gene and the disease.
asthma (continued). "IFT20 deficiency in CD4+ T cells reduced airway inflammation in OVA-induced and protease-induced asthma models." (PMID 37029318, 2023). "Previous work indicated that Tc2 cells express the prostaglandin D2 receptor CRTH229,30, which is in line with the increased abundance of CRTH2+CD4- T cells we detected in a different asthma patient cohort." (PMID 37612281, 2023). "In peripheral blood, it was found that B cells and CD4/CD8 were higher in the asthmatic bronchitis group than that in the asthma children, while levels of CD8+ T cells, and NK cells were lower." (PMID 37893483, 2023). "The expression of Id1 as well as Il9 was significantly increased in CD4 T cells from the asthma‐induced mice, highlighting the physiological significance of Id1." (PMID 37867222, 2023). "Functional enrichment analysis of genome-wide association study (GWAS)-summary statistics has suggested that CD4+ T-cells play an important role in asthma pathogenesis." (PMID 38129444, 2023). "For example, hyperactivation of CD4+ T cells can result in asthma and autoimmune disease, whereas hypoactivation of these cells can lead to immunodeficiency syndrome." (PMID 37029318, 2023). "Aside from Th2 cells, Th17 cells and the IL-17A they produce are the most frequently observed and studied CD4 T cell populations in asthma." (PMID 37163370, 2023). "Peptidoglycan recognition protein 1 (PGLYRP1), an innate proinflammatory and antibacterial protein, has been linked with asthma in animal models, with PGLYRP1-deficient mice exhibiting a decreased Th2/CD4+ response, with a less severe phenotype." (PMID 37474963, 2023). "More than half of the pulmonary CD4+CD3+ cells in moderate-to-severe asthma patients were natural killer T cells, with elevated invariant T-cell receptor expression." (PMID 37208441, 2023). "These and other asthma risk variants at 17q21 (rs4065275, rs12936231, rs7216389) increase ORMDL3 expression on CD4+ T cells, reducing interleukin-2 production." (PMID 37762787, 2023). "When the Cd4-Cre::Acc1fl/fl and Acc1fl/fl control mice were induced to undergo OVA-mediated asthma, we indeed observed that the loss of ACC1 expression attenuated AHR and the total immune-cell numbers in the lung and the bronchoalveolar lavage fluid (BALF)." (PMID 37917548, 2023). "During the comorbidity asthma and acute pneumonia, we found an increase in CD4+IL-17+ cells in the lungs of WT animals exposed to the allergen and infected with S. pneumoniae." (PMID 37445595, 2023). "This study showed that Cd4-Cre::Acc1fl/fl mice exhibited attenuated AHR and airway inflammation in OVA- and HDM-induced asthma models due to the enhanced apoptosis and loss of Gata3, Il4, and Il13 expression in lung iNKT cells." (PMID 37917548, 2023). "By integrating publicly available genetic and protein–protein interaction data, we identified PTPRC, a gene previously identified as a master regulator of asthma gene expression profile from nasal brushing, as a master regulator in peripheral CD4+ T-cells." (PMID 38129444, 2023). "In sum, TFH display substantial functional plasticity with other CD4 T cell subsets, including Th2 cells in asthma." (PMID 37163370, 2023). "MiR-146a and miR-146b were upregulated in splenic CD4+ T cells of an OVA-induced mouse asthma model, while miR-146a was downregulated after dexamethasone treatment." (PMID 36865391, 2023). "We presented the results of a Weighted Gene Co-expression Network Analysis on CD4+ T-cells in patients with well-controlled asthma and healthy controls." (PMID 38129444, 2023). "We identified PTPRC, a gene previously identified in GWAS studies, which also showed evidence of colocalisation with T-cell specific eQTL from GENCORD, as a putative master regulator in CD4+ T-cell asthma gene expression profile." (PMID 38129444, 2023).
asthma (continued). "To date, there exist several animal experiments and clinical studies to verify the effect of acupuncture treatment on asthma, mainly by regulating the number and activity of CD4+ T cells to play an anti-inflammatory role." (PMID 37090714, 2023). "Coproduction of IL-17 alongside Th2 cytokines by CD4 T cells has also been observed in individuals with asthma, particularly those with severe, steroid-resistant asthma." (PMID 37163370, 2023). "Estrogen contributes to the inflammatory pathway by stimulating hormone receptors on dendritic cells, mast cells, CD4+ T lymphocytes (Th2), and eosinophils, possibly contributing to a higher number of asthma exacerbations in females." (PMID 38274465, 2023). "In asthma, chronic inflammation is mainly characterized by an eosinophilic infiltrate and CD4+ cells, and, in COPD, the predominant inflammation is caused by neutrophils and CD8+ cells." (PMID 37511021, 2023). "CD4+ T lymphocytes regulate chronic inflammation in asthma via the release of Th2 adaptive cytokines, which can lead to the observed changes in airway hyperresponsiveness, mucus production, and airway remodeling." (PMID 37377691, 2023). "Note that the frequency of IL5+ and IL13+ CD4 T cells was low in control wild type mice in our asthma model." (PMID 37575259, 2023). "Circ_0005519 was upregulated in CD4+ T cells in asthma patients by inducing the expression of IL-13 and IL-6 in CD4+ T cells." (PMID 38187401, 2023). "Some scholars have pointed out that compared to CD4+ T cells, CD8+ T cells have a stronger association with the severity of asthma." (PMID 37893483, 2023). "It is known that, under specific conditions, naive CD4 + T cells are atypically activated, thus, they differentiate into a Th subpopulation cell type that drives the disease; this is a typical feature of asthma." (PMID 37245015, 2023). "In conclusion, CD4+ T-cells have been previously identified as a critically important cell type in asthma." (PMID 38129444, 2023). "The immunomodulatory properties of macrolides are well-recognized; for example, asthma patients receiving azithromycin exhibit lower IL-5 expression in CD4+ cells isolated from peripheral blood mononuclear cells." (PMID 37347185, 2023). "Mechanistically, CD4+ T cells and ILC2s regulate asthma by promoting the production of IL-13 amplifying type II inflammation." (PMID 35656293, 2022). "Tissue-resident memory CD4 T cells (Trm) are thought to be a major contributor to asthma relapse, but the role of circulatory T cells in asthma exacerbations or to maintaining the population of lung Trm cells is not fully understood." (PMID 35936001, 2022). "Th1 and Th2 cells are two different subgroups of CD4+ Th cells, and CD4+ Th cells are important immune cells in the human body that participate in the immune response and play an important role in the pathogenesis of asthma." (PMID 35186104, 2022). "The expression of TRPA1 is increased in lung tissues and CD4+ T cells in an OVA-induced mouse model of asthma, accompanied with the development and exacerbation of asthma." (PMID 35784284, 2022). "They found that CD4+ T cells were predominant cell type in severe asthma, and exhibited a pro-inflammatory signature of increased JAK1 expression." (PMID 36524132, 2022). "It is confirmed that the CD4+ cells can develop into the Th1 and Th2 sub-groups, which can secrete a variety of cytokines and play immunomodulatory roles in the pathogenesis of asthma." (PMID 35859797, 2022). "LURAP1L gene expression was found significantly increased in the CD4+ T-cells of obese compared to normal-weighted children with asthma." (PMID 35910207, 2022). "CD4+ T cells, particularly T helper (Th) 2 cells, and their specific cytokines are important mediators in asthma pathogenesis." (PMID 35454142, 2022). "For asthma, a chronic airway inflammatory disease usually driven by the Th2 subset of CD4+ T lymphocytes, 67% (2/3) of the trials showed improvement in symptom scores and lung function." (PMID 35465348, 2022).
asthma (continued). "T lymphocytes, especially CD4+ T-cells and related cytokines have been proved to play an important role in the development of asthma." (PMID 35745240, 2022). "Among the asthma subtypes, eosinophilic and T2-high asthma is the most well-studied, which is featured by excessive eosinophil infiltration into the airways and a CD4+ T cell-driven type 2 immune response leading to a typical Th2 profile." (PMID 35093168, 2022). "It was unique to the present case that cytotoxic T lymphocyte antigen 4 (CTLA-4) in CD4+ Forkhead box P3 (Foxp3) + T cells were upregulated in the early phase before the development of asthma attacks." (PMID 35029177, 2022). "Of all the participants, one neonate in the HC group was diagnosed with both asthma and atopic dermatitis, and was surprisingly found to have the highest expression level of Il-4 in cord blood CD4+ T-cells." (PMID 35745240, 2022). "Cytotoxic T lymphocyte antigen 4 (CTLA-4) in CD4+ FOX3+ T cells was upregulated in the early phase before the development of asthma attacks." (PMID 35029177, 2022). "A new CD4+ helper T-cell subpopulation Th17 is recently identified, which produces the cytokine IL-17 that plays an important role in the development of asthma pathogenesis." (PMID 35815290, 2022). "CD4+ T cells initiate inflammatory and allergic responses in allergic asthma, leading to two asthma phenotypes: Th2 and non-Th2." (PMID 35769905, 2022). "Here, we used a house dust mite allergen-based murine model of asthma relapse, and monitored the development of lung effector/Trm phenotype CD44hiCD62LloCD69+ CD4 T cells." (PMID 35936001, 2022). "IL-10 is reported to block the conversion from naïve CD4+ T cells to Th2, alleviating the symptoms of asthma." (PMID 35812246, 2022). "It is found that circ-0005519 is abnormally expressed in CD4+ T cells of asthma patients, and it can regulate let-7a-5p in CD4+ T cells to induce the expression of cytokines IL-13 and IL-6." (PMID 35806027, 2022). "The polarization of CD4+ T cells into different T helper subsets is an important process in many diseases, including asthma." (PMID 36611927, 2022). "The levels of CD4+ and CD4+/CD8+ in the recurrent infection group were significantly higher than those in the asthma group, and CD8+ levels were significantly lower than those in the asthma group." (PMID 35991273, 2022). "TSLP is crucial for differentiating dendritic cell–mediated CD4+ T-cells into Th2 cells, and it is closely related to allergic diseases such as asthma, AD, allergic rhinoconjunctivitis, and eosinophilic esophagitis." (PMID 36235405, 2022). "The airway inflammatory microenvironment of asthma has a strong chemoattraction to mature CD4+T cells and eosinophils, which leads to severe type Th2 asthma and is accompanied with high levels of eosinophils in blood and sputum." (PMID 35958837, 2022). "Meanwhile, the Flow cytometry results revealed the higher proportion of CD4+T cells secreting IL-9 in the PBMCsof the asthma mice." (PMID 36253857, 2022). "AR signalling induced by androgens stabilizes CD4+ regulatory T cells (Tregs) suppressive function, providing a mechanism for higher prevalence of asthma in women compared with men." (PMID 36038873, 2022). "The co-expression of the TNF receptors was assayed both in RA patients or asthma patients subdivided into groups according to disease duration and in healthy individuals on cells of T-helper subpopulations: CD4+, CD4+CD25+, CD4+CD45RA+, and CD4+CD45R0+ cells." (PMID 36611799, 2022). "A previous animal study indicated that CD4+CD25+FoxP3+ Tregs exerted an antiasthmatic effect in the asthma mouse model." (PMID 35812246, 2022). "Eosinophils, which were reduced in numbers in Lsp1−/− asthmatic mice, produce IL-16 to attract CD4+ T cell in asthma." (PMID 35733161, 2022). "On one hand, miRNAs regulate airway inflammation of childhood asthma by increasing Th2 cytokine secretion to decrease Th1 cytokine secretion and promote the differentiation of CD4+ T cells into Th2." (PMID 35656293, 2022).
asthma (continued). "LncRNAs and miRNAs alone have been shown to play regulatory roles in asthma by regulating CD4+ T-cell function." (PMID 35769905, 2022). "Th9 cells as a recently identified subset of CD4+ T effector cells are involved in the pathogenesis of allergy and asthma and play an important role in anti-tumor immunity." (PMID 36241625, 2022). "The cytokines secreted by CD4+ T-cells, typically, type 2 cytokines such as IL-4, IL-5, and IL-13, are closely involved in asthma." (PMID 35745240, 2022). "CXCR5 can also be expressed by follicular helper T (TFH) cells subset CXCR5+CD4+ T and played an essential role in enhancing IgE production in asthma." (PMID 35165593, 2022). "Although further studies are needed to decipher the molecular links between in utero nutrients and asthma, our study suggested the important role of early-stage nutrition in modulating CD4+ T-cell functions in both murine models and human beings." (PMID 35745240, 2022). "Quercetin regulates Th1/Th2 balance in mouse models of asthma as well as human peripheral blood derived CD4+ T cells." (PMID 36235240, 2022). "Genetic factors and activation of bronchial epithelial cells in asthma or cystic fibrosis are responsible for CD4+Th2 lymphocyte activation and production of A.f-sIgE, A.f-sIgG and A.f-sIgA." (PMID 35983066, 2022). "The imbalance of CD4+T cell subsets (Th1/Th2) leads to the destruction of the tissue structure by immune cells which is an important pathogenesis of asthma." (PMID 36212941, 2022). "In this review, we investigate the effects of crosstalk between the microbiota and CD4+ T cells on the development of asthma." (PMID 34769255, 2021). "It has been well established that CD4+ T lymphocytes play a crucial role in the initiation, progression, and persistence of asthma." (PMID 34204767, 2021). "To further evaluate its contribution to human asthma, we assayed Spry2 expression in CD4+ T cells from blood and BAL from patients with asthma and disease controls by flow cytometry." (PMID 33684096, 2021). "Proper classification of the asthma phenotype based on CD4+ T cells is essential to determine the optimal asthma treatment and accurately predict the prognosis." (PMID 34769255, 2021). "Asthma‐associated polymorphisms at the locus 17q12‐21 mediate the expression and methylation of the GSDMA gene in CD4+ T cells." (PMID 34459122, 2021). "In general, CD4+ contributes to enhancement and proliferation of Th2 cells, which can be a useful step in ameliorating asthma." (PMID 33784348, 2021). "The study included 29 pediatric patients with asthma, 22 healthy volunteers, ovalbumin-induced murine asthma models, and mouse naive CD4+ T cells." (PMID 33980319, 2021). "We found that the level of CD4+CCR6+CRTh2+ memory Th2 cells in the asthma diagnosed group was significantly higher than those in the non-asthma diagnosed group." (PMID 34090369, 2021). "Eosinophilic inflammatory response, which is characteristic of asthma, is known to be induced by IL-4, IL-5, and IL-13 produced by CD4+ T helper type 2 (Th2) cells." (PMID 34576095, 2021). "Spry2 expression was higher in blood and airway CD4+ T cells from patients with asthma, and Spry2 knockdown impaired human T cell proliferation and cytokine production." (PMID 33684096, 2021). "Second, we sorted naïve CD4 T cells from the peripheral blood of asthma patients and explore the expression and the role of SERPINB10 in Th1 and Th2 cells." (PMID 34126986, 2021). "Studies have shown that ILC2s potentiate CD4 T helper cell activation in asthma, which is the effector cell in the complex pathophysiology of inflammation in asthma." (PMID 35126350, 2021). "In T2-high asthma, CD4+T helper 2 (Th2) cells and innate lymphoid cells group 2 (ILC2), eosinophils, immunoglobulin E (IgE) and T2 cytokines such as interleukin (IL)-4, IL-5 and IL-13 contribute to its pathogenesis." (PMID 34777398, 2021).
asthma (continued). "The asthma phenotype can change depending on which type of CD4 T cell is differentiated; consequently, the response to asthma drugs can change accordingly." (PMID 34769255, 2021). "Given the pivotal role that Th2 cells and cytokines play in asthma pathophysiology, the severely diminished Th2 responses observed in CerS2 null CD4+ T cells are likely to contribute to the decreased severity of asthma patients." (PMID 33800208, 2021). "Significant roles of CD4+CD25+Foxp3+ Treg cells have previously been identified in asthma regulation." (PMID 33784348, 2021). "A previous study has shown that bronchoalveolar lavage samples with elevated CD4+ cells that expressed both IL-4 and IL-17 predicted greater asthma severity." (PMID 35387066, 2021). "Although various immune cells are involved in the pathogenesis of Th2-asthma, the Th2, Th9, and T follicular helper cell (Tfh) CD4+ T cell subtypes play particularly key roles." (PMID 34769255, 2021). "Elucidating the biological roles of CD4+ T cells is thus essential for developing effective asthma treatments and predicting a patient’s prognosis." (PMID 34769255, 2021). "Cluster 13, which is defined as CD4+ naïve T, was significant in patients with acute pneumonia, stable pneumonia, acute asthma and asthma as compared with healthy volunteers, patients with AECOPD, COPD and LC." (PMID 34841705, 2021). "Dysbiosis caused by an imbalance in the microbiota homeostasis alters the differentiation of CD4+ T cells, resulting in asthma aggravation." (PMID 34769255, 2021). "Subsets of CD4+ T cells, such as Th1, Th2, and Th17 have been shown to differentially contribute to the initiation and perpetuation of specific asthma phenotypes." (PMID 34576307, 2021). "Detecting of CD4+CCR6+CRTh2+ memory Th2 cells in BALF would be more valuable in predict future asthma since those cells are mainly resident in airway." (PMID 34090369, 2021). "In this section, we discuss how alterations in CD4+ T cells during dysbiosis affect the pathogenesis of asthma." (PMID 34769255, 2021). "Thymic stromal lymphopoietin (TSLP) is a cytokine that acts directly on CD4+ T cells and dendritic cells to promote progression of asthma, atopic dermatitis, and allergic inflammation." (PMID 33439121, 2021). "Logistic regression analysis indicated that circulating CD4+CCR6+CRTh2+ cells (EXP, 8.986; 95 % CI,1.886–42.816) and wheezing frequency(EXP, 0.127; 95 % CI, 0.023–0.703)were high risk factors for asthma." (PMID 34090369, 2021). "In the pathogenesis of asthma, CD4+ T cells synthesize proinflammatory cytokines such as IL-4, IL-5 and IL-13." (PMID 34209324, 2021). "Lung inflammation in asthma is typically orchestrated by activation of CD4+ T lymphocytes which release a wide range of cytokines, to trigger IgE production by B lymphocytes, stimulating the release of inflammatory mediators from immune cells." (PMID 33942458, 2021). "A study has shown that MBD2 gene silencing significantly lowers the IL-17 expression as increased expression increases the IL-17 expression from splenic CD4+ T cells in an animal model of asthma." (PMID 35096261, 2021). "The same study revealed that various environmental factors that affect these bacteria also affect the differentiation of CD4+ T cells, resulting in the development of asthma." (PMID 34769255, 2021). "In this review, we discuss the detailed mechanism of the pathogenesis of asthma as it relates to Th2-asthma and non-Th2 asthma, with a particular focus on CD4+ T cells." (PMID 34769255, 2021). "Previous studies indicate that exposure to 2-ethyl-1-hexanol increases CD4 + T cell activation and asthma prevalence." (PMID 34226570, 2021). "Recent literature indicates that imbalances between beneficial and harmful bacteria affect the differentiation of CD4+ T cells, leading to the development of asthma." (PMID 34769255, 2021).